ZSWIM6 (zinc finger SWIM-type containing 6)
Description:
involved in nervous system development, important for striatal morphology and motor regulation.
Synonyms: KIAA1577; AFND; NEDMAGA
Tractability: PROTAC: ubiquitination databases record sites on it.
Gene: Protein-coding gene on chromosome 5 (61,332,258 to 61,546,172, forward strand). Ensembl gene ENSG00000130449.
Subcellular location (Human Protein Atlas): Cytosol
Gene Ontology:
Molecular function: zinc ion binding
Biological process: striatal medium spiny neuron differentiation
Cellular component: Cul2-RING ubiquitin ligase complex
Genetic constraint (gnomAD): Loss-of-function variants: 8 observed, 99.05 expected, observed/expected ratio (o/e) 0.0808, 90% interval 0.046 to 0.15. The upper end of that interval is the gene's LOEUF score, 0.15, which puts it in group 1 of 6, group 1 being the genes least tolerant of losing a copy. Missense variants: 1,058 observed, 1,394.3 expected, observed/expected ratio (o/e) 0.76, 90% interval 0.72 to 0.8. Synonymous variants: 555 observed, 535.65 expected, observed/expected ratio (o/e) 1.04, 90% interval 0.97 to 1.11.
Gene-disease validity (ClinGen):
ClinGen rates the evidence that ZSWIM6 causes each of these diseases.
acromelic frontonasal dysostosis (autosomal dominant): Definitive.
Homologues: Orthologues: macaque ZSWIM6 (99% identical), dog ZSWIM6 (98% identical), pig ZSWIM6 (97% identical), mouse Zswim6 (96% identical), rat Zswim6 (96% identical), tropical clawed frog zswim6 (89% identical), chimpanzee ZSWIM6 (82% identical), guinea pig ZSWIM6 (82% identical), rabbit ZSWIM6 (80% identical), zebrafish zswim6 (67% identical). Paralogues in human: ZSWIM5 (71% identical), ZSWIM4 (58% identical), ZSWIM8 (28% identical).
Diseases named in the same sentence as ZSWIM6 in open-access papers:
ZSWIM6 is named in the same sentence as 26 diseases in open-access papers, as found by Europe PMC text mining. Sharing a sentence is not in itself a finding about the gene and the disease. The quoted sentences say what the papers report.
schizophrenia (5 papers, 2019 to 2024). A major psychotic disorder characterized by abnormalities in the perception or expression of reality. "Clinical studies have linked Zswim6 mutations to developmental and neurological diseases, including schizophrenia." (PMID 34054439, 2021). "Additionally, another association signal at gene ZSWIM6 located on chromosome 5q12.1 has been found as GWAS loci for schizophrenia." (PMID 35286190, 2022). "Interestingly, Zswim6 is expressed in the medial habenula in which the schizophrenia-risk gene ErbB4 is also highly expressed." (PMID 34054439, 2021). "Interestingly, ZSWIM6 is ranked in the top five schizophrenia-associated genes that are linked to the MAPK signaling pathway." (PMID 34054439, 2021). "Among the nine genome-wide significant loci, the identified top regions are pinpointed to previously reported GWAS loci for bipolar disorder (miR-2113/POUSF2 and LINC01239) and schizophrenia loci (ZSWIM6)." (PMID 35286190, 2022). "Given the involvement of Zswim6 in schizophrenia and schizophrenia as a neurodevelopmental disease, it is important to understand the spatiotemporal expression pattern of Zswim6 in the developing brain." (PMID 34054439, 2021). "At E15.5 and E17.5, Zswim6 was expressed in several key brain regions that were involved in the pathogenesis of schizophrenia, including the striatum, cerebral cortex, hippocampus, and medial habenular nucleus." (PMID 34054439, 2021). "Loss of zinc-finger SWIM domain-containing protein 6 (ZSWIM6), another schizophrenia-risk gene, has been shown to decrease neurite arborization and the number of dendritic spines in SPNs." (PMID 31097624, 2019). "Given that Zswim6 is associated with schizophrenia, it is of interest to investigate whether abnormal striatal dopamine neurotransmission occurs in Zswim6 knockout mice that may contribute to schizophrenia-like phenotypes." (PMID 34054439, 2021).
acromelic frontonasal dysostosis (4 papers, 2017 to 2024). "A mutation in ZSWIM6 causes acromelic frontonasal dysostosis (AFND) which is characterized by craniofacial, brain, and limb malformations, perhaps by inhibiting Hedgehog signaling." (PMID 38177922, 2024). "In humans, pathogenic variants in the ZSWIM6 gene (OMIM 615951) are associated to acromelic frontonasal dysostosis and neurodevelopmental disorder with movement abnormalities, abnormal gait, and autistic features." (PMID 33652974, 2021).
autism (3 papers, 2019 to 2025). Persistent deficits in social interaction and communication and interaction as well as a markedly restricted repertoire of activity and interest as well as repetitive patterns of behavior. "Eight differentially expressed genes (DEGs) were identified exclusively in this group, including Homer1 and Zswim6, both of which are listed as high-confidence autism risk genes in the SFARI Gene database." (PMID 40801633, 2025). "We further implicated autism, metabolic syndrome, and neuroticism as genetically linked to ARFID via common variants, and identified ZSWIM6, a known neurodevelopment gene, as the first putative genetic association with ARFID." (PMID 34177659, 2021).
dental caries (1 paper, 2023). The decay of a tooth, in which it becomes softened, discolored, and/or porous. "Furthermore, ZSWIM6, associated with dental caries formation, was found to have a deletion of 6 bp in its CDS in BKY compared to Han1, leading to the loss of two glycines in its protein sequence." (PMID 37928602, 2023).
developmental delay (1 paper, 2024). "The two patients in our study with ZSWIM6 variants presented with overlapping features of muscle weakness and developmental delay, despite being classified into different disease categories (CM and MD) based on their initial clinical assessment." (PMID 38818036, 2024).
head and neck squamous cell carcinoma (1 paper, 2025). A squamous cell carcinoma that arises from any of the following anatomic sites: lip and oral cavity, nasal cavity, paranasal sinuses, pharynx, larynx, and salivary glands. "RNPS1 directly interacts with NAT10, inhibiting the ubiquitination degradation of NAT10 by E3 ubiquitin ligase, zinc finger SWIM domain-containing protein 6 (ZSWIM6), thereby promoting translation process of genes regulating malignant progression in head and neck squamous cell carcinoma." (PMID 40588654, 2025).
Intellectual disability (1 paper, 2024). "The ZSWIM6 gene has been associated with neurodevelopmental disorder with movement abnormalities and/or seizures, a condition characterized by a wide range of clinical manifestations, including intellectual disability, seizures, and abnormal movements." (PMID 38818036, 2024).
vascular malformation (1 paper, 2021). A non-neoplastic disorder that is the result of defects of vascular morphogenesis. "Assuming a spontaneous de novo mutation event, one of the identified variants found in the PREX1, UBE3B, PCDHGA2, and ZSWIM6 genes may represent a possible candidate pathogenic variant for this rare form of vascular malformation." (PMID 33652974, 2021).
neurodevelopmental disorder (7 papers, 2019 to 2026). A behavioral and cognitive disorder with onset during the developmental period that involves impaired or aberrant development of intellectual, motor, or social functions. "The most commonly mutated gene was ZSWIM6, implicated in neurodevelopmental disorder with movement abnormalities, abnormal gait, and autistic features." (PMID 38818036, 2024). "There are some reports of chromosomal microdeletions in the ZSWIM6 region; however, patients with microdeletions involving ZSWIM6 show milder neurodevelopmental disorders than patients with the p.Arg913* ZSWIM6 variant." (PMID 33958584, 2021).
dysostosis (2 papers, 2016). A group of disorders in which the skeletal involvement is predominantly manifested as abnormalities of individual bones or in a group of bones. "Acromelic frontonasal dysostosis and ZSWIM6 mutation: phenotypic spectrum and mosaicism." (PMID 27896281, 2016).
neurological disorders (2 papers, 2021 to 2022). "Previous studies found that mutations of the ZSWIM6 gene affect developmental and neurological disorders." (PMID 36290392, 2022). "In summary, the comprehensive analysis provides an anatomical framework for the study of Zswim6 function and Zswim6-associated neurological disorders." (PMID 34054439, 2021). "The cell type characterization of Zswim6 expression will help explore the neuronal function of Zswim6 and the pathology of Zswim6-associated neurological diseases." (PMID 34054439, 2021). "It would be of interest to identify non-coding variants of Zswim6 and study the non-coding regions that may regulate Zswim6 expression, which may help understand the pathology of Zswim6-associated neurological disorders." (PMID 34054439, 2021).
cardiovascular disease (1 paper, 2013). "At 4 weeks post-MI, 4 genes (DOCK9, MBNL1, RRAD, and ZSWIM6) by all of 37 unique altered transcripts were related to cardiovascular disease." (PMID 23372767, 2013).
ZSWIM6 also shares sentences with these, for which no sentence is quoted: acute myelogenous leukemia (1 paper); congenital myopathies (1); epilepsy (1); frontonasal dysplasia (1); growth deficiency (1); hearing loss (1); Lowe syndrome (1); metabolic (1); metabolic syndrome (1); microcephaly (1); muscular dystrophies (1); Neurodevelopmental delay (1); thoracic aortic aneurysm (1); X-linked disease (1).